EZH2 (enhancer of zeste 2 polycomb repressive complex 2 subunit)
Diseases named in the same sentence as EZH2 in open-access papers (continued):
Sharing a sentence is not in itself a finding about the gene and the disease.
breast cancer (continued). "Diagnocode consisted with L-DNA tested for the ability to hybridize with different concentrations of an oligonucleotide sequence from the breast cancer-specific enhancer zeste homolog 2 (EZH2, CAGATTTCTTCCCAGTCTGGC)." (PMID 26678430, 2015). "EZH2 regulates invasion of breast cancer mainly through mediating transcriptional silencing of the tumor suppressor genes, including E-cadherin by regulating histone modifications in the promoters of these target genes, including H3K27me3." (PMID 26378045, 2015). "EZH2 was also reported to be highly expressed in breast cancer and prostate cancer; moreover, EZH2 inhibitors have been considered a promising therapy for certain types of tumors." (PMID 27462425, 2015). "A previous study in breast cancer also showed that low EZH2 expression is correlated with better Distant Disease Free Survival (DDFS), corroborating our findings." (PMID 25762637, 2015). "More relevant to the present work, previous studies reported high levels of EZH2 in carcinomas such as prostate and breast cancer." (PMID 26637281, 2015). "In support of a protective role for PRC2 in breast cancer, we found that mutations in PRC2 core components are associated with a poor prognosis and documented several mutations in EZH2 and PRC2 core component SUZ12 in breast cancer metastases." (PMID 26637281, 2015). "Previous studies show that lncRNAs such as HOTAIR play important roles in facilitating genome-wide occupancy of EZH2 onto chromatin in breast cancer cells." (PMID 26516927, 2015). "In ERα-positive luminal-like breast cancer cells, EZH2 can form transcription complexes with ERα or its co-activators, facilitating the TCF/β-CATENIN-mediated gene transcription." (PMID 26580594, 2015). "Even more surprising, the levels of the enzyme and the mark were found to be anti-correlated between the different breast cancer subtypes, and, while high expression of EZH2 correlates with poor prognosis, high levels of H3K27me3 correlate with good prognosis." (PMID 26637281, 2015). "Consistent with our results, HOTAIR is over-expressed in early and metastatic breast cancer cells, serves as a prognostic factor for glioma patient and promotes glioblastoma cell cycle progression in an EZH2 dependent manner." (PMID 26183397, 2015). "The same enrichment tests were repeated using target gene sets identified in an EZH2 siRNA knockdown study in another breast cancer cell line, MCF-7." (PMID 26300989, 2015). "EZH2 has been found frequently overexpressed in variety of human cancers such as prostate and breast cancer." (PMID 26516927, 2015). "This study validates previous findings in individual HMTs, namely that WHSC1L1 is highly amplified/overexpressed in Luminal subtypes, and EZH2 is highly expressed in basal-like breast cancer." (PMID 25537518, 2015). "Since our analyses indicated that impaired PRC2 function is associated with poor prognosis, we used CRISPR/CAS9-based genome engineering tools to delete EZH2 in a cellular model of human breast cancer." (PMID 26637281, 2015). "We analyzed EZH2 and H3K27me3 levels by IHC in two previously characterized patient-derived xenografts (PDXs) of estrogen-positive breast cancer." (PMID 26637281, 2015). "Since high EZH2 expression has also been reported in breast cancer, we next turned to a mouse model eliciting mammary tumors upon mammary-specific expression of the activated form of Notch1 (N1ICD)." (PMID 26637281, 2015). "A similar analysis on a breast cancer cohort comprising 146 samples from the four main molecular subtypes confirmed that EZH2 expression correlates with proliferation markers." (PMID 26637281, 2015). "We thus sought to assess the impact of modulating proliferation on the levels of EZH2 and H3K27me3 in the context of human breast cancers." (PMID 26637281, 2015).
breast cancer (continued). "Involvement of CSCs in tamoxifen resistance of breast cancer cells has been reported, which appears to be mechanistically linked with higher expression of CXCR4, STAT3, Sox2, EZH2, and lower expression of CD24." (PMID 26206152, 2015). "EZH2 was correlated with histological grade, estrogen receptor expression, and progesterone receptor expression in breast cancer." (PMID 25974088, 2015). "BPA increases the expression of Enhancer of Zeste Homolog 2 (EZH2), a histone methyl transferase, in breast cancer cell line." (PMID 26097467, 2015). "They further showed that HIF1α, a known mediator of radioresistance in breast cancer, activates the EZH2 gene and increases EZH2 expression under hypoxic conditions." (PMID 25051981, 2014). "One example is the polycomb complex protein EZH2 that acts as an oncogene i.e. in prostate and breast cancer, while it suppresses T-cell leukemia development in mice." (PMID 24740120, 2014). "In breast cancer, abnormally elevated EZH2 levels have been found to be highly correlated with tumor cell invasiveness and increased proliferation rates, poor prognosis." (PMID 25159232, 2014). "In ER-positive luminal-like breast cancer cells, EZH2 also acts as an activator independently of its SET domain through association with ER and WNT signaling components TCF/β-catenin to activate ER target genes such as c-myc and cyclin D1 (middle left)." (PMID 25520914, 2014). "MiR-214 has also been found to be decreased in breast cancer and contribute to breast tumourigenesis by allowing aberrantly elevated oncogene Ezh2 accumulation and subsequent unchecked cell proliferation and invasion." (PMID 24614175, 2014). "Up-regulation of miR-26a promotes apoptosis in rat neonatal cardiomyocytes via the caspase-3 pathway while down-regulation of miR-26a antagonizes apoptosis by targeting MTDH and EZH2 in breast cancer." (PMID 25070658, 2014). "Our previous work suggested EZH2-mediated down-regulation of multiple tumor suppressor miRs such as miR-26, 31, 181a, 181b, 200b, 200c and 203 in prostate and breast cancer." (PMID 25115393, 2014). "Overexpression of EZH2 has been detected in breast cancer, with increased EZH2 levels correlating with higher proliferation rates, neoplastic transformation and more aggressive cancer subtypes." (PMID 25479686, 2014). "Up to now, the role of Polycomb in breast cancer has been mainly addressed to investigate the expression or the function of two Polycomb proteins, EZH2 and BMI1 (PRC2 and PRC1 complexes, respectively)." (PMID 24742605, 2014). "Knockdown of EZH2 with siRNA inhibits breast cancer cell proliferation, and pharmacological inhibition of EZH2 results in apoptosis of breast cancer cells." (PMID 24745014, 2014). "Enhancer of zeste homolog 2 (EZH2), a member of the polycomb group proteins, has been shown to promote cancer progression and breast cancer stem cell (CSC) expansion." (PMID 25051981, 2014). "Further studies are warranted to elucidate this paradox by examining how EZH2 activates radiation resistance mechanisms in breast cancer cells." (PMID 25051981, 2014). "A functional link between GATA3 expression and the histone methyltransferase enhancer of zeste homolog 2 (EZH2) has been suggested, since EZH2 knockdown in basal-like breast cancer cells promotes the increase of GATA3 expression levels." (PMID 25479686, 2014). "This suggested to us that EZH2 would be a particularly attractive candidate to investigate with respect to these two breast cancer cell lines." (PMID 23826629, 2013). "Based on our study of the literature, we recognized that EZH2 expression has two implications in breast cancer." (PMID 24266940, 2013). "For instance, the Suz12 subunit is overexpressed in colon and breast cancers, and Ezh2 is upregulated in a number of tumors, including Hodgkin lymphoma, prostate cancer, and breast cancer." (PMID 24070194, 2013).
breast cancer (continued). "For example, EZH2 is often expressed at higher levels in breast cancer and its overexpression correlates with aggressiveness and poor prognosis." (PMID 24294976, 2013). "Similar to our results for SETD4, EZH2 transcript and protein expression are elevated in breast cancer." (PMID 24738023, 2013). "Some studies suggest that EZH2 expression is correlated with reduced E-cadherin expression in breast cancer and is an independent prediction of breast cancer recurrence and death." (PMID 24266940, 2013). "It is postulated that EZH2 promotes breast cancer progression by transcriptional repression of tumor suppressors and by maintaining the cells in a stem cells state." (PMID 24266940, 2013). "Taken together, our data point to the possibility that mammary cancer cells share a chromatin state characterized by elevated H3K27me3 levels and EZH2 expression." (PMID 23826629, 2013). "Consistent with data suggesting EZH2 regulates RORα levels, the authors showed that breast cancer cells and tumors which overexpress EZH2 have lower RORα levels compared to normal controls." (PMID 24028781, 2013). "EZH2 protein expression was observed primarily in the nucleus, and its expression was significantly increased in invasive carcinoma and breast cancer metastases." (PMID 24738023, 2013). "For instance, EZH2 and SMYD3 are overexpressed in various types of cancer, including breast cancer and have been closely linked to breast carcinogenesis through distinct mechanisms." (PMID 24738023, 2013). "For example, the polycomb group protein EZH2 catalyses histone modifications, promotes DNA methylation, and is a predictive marker of invasive growth in metastatic prostate and breast cancers." (PMID 23991171, 2013). "EZH2 is a known marker of aggressive breast cancer, specifically through an influence on cancer stem cells, but a link to EMT has not yet been described." (PMID 24367927, 2013). "Looking within tumor types, high HDAC4 activation was seen in basal breast cancer and mesenchymal glioblastoma (GBM), while high EZH2 activation was seen in luminal breast cancer and proneural GBM." (PMID 24079712, 2013). "The available evidence suggests that EZH2 has oncogenic properties, and its overexpression in prostate and breast cancers promotes tumorigenesis, invasiveness and metastasis." (PMID 24348513, 2013). "We proposed that all ILC and lobular carcinomas in situ showed immunohistochemically EZH2 overexpression because most of them have lost the expression of E-cadherin." (PMID 24266940, 2013). "BPA effects on histone modifications were found to increase expression of the histone methyltransferase Enhancer of Zeste Homolog 2 (EZH2) level in human breast cancer MCF7 cells and mammary glands of six-week-old mice exposed to BPA in utero." (PMID 22949852, 2012). "EZH2 is a potential cancer biomarker as overexpression of the nuclear protein is seen in a variety of aggressive cancers, including breast cancer, prostate cancer and glioblastoma multiforme." (PMID 22412953, 2012). "Downregulation of EZH2 expression in breast cancer cells led to decreased proliferation, delayed cell-cycle transition, and upregulation of the BRCA1 protein." (PMID 23133536, 2012). "Our study correlates decreased expression of MHC II in breast cancer cells with epigenetic suppression of CIITApIV by the histone methyltransferase EZH2." (PMID 22563434, 2012). "Dimri and coworkers showed that the aberrant expression of PcG protein enhancer of zeste homologue 2 (EZH2) can be suppressed by dietary omega-3 polyunsaturated fatty acids (PUFAs), leading to decrease in the invasion potential of breast cancer cells." (PMID 22550415, 2012). "Histone H3 was found to be trimethylated at lysine 27 by BPA effect on EZH2 in a human breast cancer cell line and mice." (PMID 22949852, 2012). "EZH2 is amplified and highly expressed in many cancers including melanoma, endometrial, prostate, and breast carcinoma." (PMID 23133536, 2012).
breast cancer (continued). "Lastly, using matched primary and metastatic breast carcinomas we determine if HOTAIR and EZH2 have increased expression in metastatic versus primary breast carcinoma." (PMID 23133536, 2012). "It has been shown that miR-26a acts via EZH2, an oncogene markedly elevated in breast cancer cells, and affects growth and tumorigenesis." (PMID 21811619, 2011). "In breast cancer, high EZH2 expression was a strong independent predictive parameter of outcome, providing a better information about CSS than other independent prognostic features." (PMID 20920340, 2010). "A similar cooperative relationship between the polycomb repressors, Ezh2, Suppressor of Zeste12, and DNA methyltransferases has been shown in HOXA9 gene silencing upon loss of p16INK4a tumor suppressor activity in breast cancer cells." (PMID 20814569, 2010). "The search results revealed that EZH2 is consistently upregulated in multiple human cancer types including breast cancer, while CDKN1C is downregulated in these tumors." (PMID 19340297, 2009). "Recently, Gonzalez and colleagues showed that knock-down of EZH2 reduced the proliferation of two ER-negative human breast cancer cell lines." (PMID 19709408, 2009). "In this study, we demonstrate that EZH2 expression is high in breast tumors from BRCA1-mutation carriers, similar to that observed in our mouse model for BRCA1-deficient breast cancer." (PMID 19709408, 2009). "We also demonstrate the prognostic value of EZH2-mediated CDKN1C repression in breast cancer and suggest its clinical significance for EZH2-targeted cancer therapeutics." (PMID 19340297, 2009). "Enhanced EZH2 expression has been previously shown to correlate with poor prognosis of breast cancer." (PMID 19340297, 2009). "The overexpression of EZH2 in all basal-like breast cancers warrants further investigation of the potential for targeting the genetic make-up of this particular breast cancer type." (PMID 19709408, 2009). "Mechanistically, this finding is consistent with the previous knowledge that overexpression of EZH2 correlates with a poor breast cancer prognosis." (PMID 19340297, 2009). "Consistent with the overexpression of EZH2 in a variety of human cancers including breast cancer, CDKN1C in these cancers is downregulated, and breast tumors expressing low levels of CDKN1C are associated with a poor prognosis." (PMID 19340297, 2009). "After comparing gene expression patterns of BRCA1-deficient mouse mammary tumors with BRCA1-proficient control tumors, we noted that Ezh2 expression was particularly high in BRCA1-deficient tumors." (PMID 19709408, 2009). "In light of the potential role of PcG proteins in cancer stem cells, we investigated the controversial role of BMI1 in breast cancer and compared it with EZH2 to obtain more of an insight into polycomb function in tumourigenesis." (PMID 19099573, 2008). "In contrast, the link between EZH2 overexpression and reduced breast cancer survival is well established." (PMID 19099573, 2008). "EZH2 overexpression correlates with late stage disease and can even be an independent predictor of aggressive breast cancer." (PMID 19099573, 2008). "Patients with HCC, prostate cancer, colorectal cancer and breast cancer were studied, and with the exception of breast cancer, T-cell reactivity to BMI-1 and/or EZH2 was observed in all groups." (PMID 17024127, 2006). "This confirms previous studies demonstrating upregulation of EZH2 expression in tumours of patients with breast cancer." (PMID 17024127, 2006). "High-level expression of EZH2 mRNA was observed in the prostate cancer cell line LNCaP, the HepG2 hepatoblastoma cell line and three breast cancer cell lines MCF7, BT549 and nDA-MB436." (PMID 17024127, 2006). "Antigen-specific cytotoxicity was observed against HLA-A0201-matched fibroblasts infected with a recombinant adenovirus encoding EZH2 (RAdEZH2) and the breast carcinoma cell line MCF7, which naturally expresses EZH2." (PMID 17024127, 2006).
breast cancer (continued). "Although an association between the tumour aggressiveness and the overexpression of EZH2 has been well documented for breast cancer and prostate cancer, little is known about the expression status of EZH2 in digestive organ cancers." (PMID 15856046, 2005). "Recently, several studies have shown that EZH2 is highly expressed in aggressive tumours, including human breast cancer, prostate cancer, and lymphomas." (PMID 15856046, 2005). "For example, one of our recent studies has established the polycomb protein EZH2 to be an independent predictor of breast cancer survival outcome." (PMID 15598354, 2004). "Additionally, the same research group discovered that EZH2-directed PROTACs concurrently target oncogenic nodes associated with EZH2 and FOXM1, thereby inhibiting breast cancer growth." (PMID 41607539, 2026). "We further investigated the impact of crotonyl-CoA on EZH2 levels in breast cancer cells." (PMID 41544165, 2026). "To investigate the role of EZH2 in HER2+ tumor progression, we crossed a genetically engineered mouse model of HER2-driven breast cancer with a conditional Ezh2 knockout strain and showed that Ezh2 is essential for accelerating tumor initiation and metastatic dissemination." (PMID 41606266, 2026). "Indeed, this is consistent with a previous study from breast cancer cells where EZH2 levels decreased following MAPK inhibition." (PMID 41147659, 2026). "Numerous studies have elucidated the complex role of EZH2 in the pathogenesis of breast cancer." (PMID 41607539, 2026). "In particular, hypoxia can increase the expression of lncRNA H19, which functions as a ceRNA to bind miRNA let-7 with EZH2 mRNA in a competitive manner, so indirectly increasing EZH2 expression and encouraging the invasion and metastasis of breast cancer cells." (PMID 41614928, 2026). "Therefore, targeting EZH2 degradation through crotonate or crotonyl-CoA supplementation represents a promising therapeutic strategy for breast cancer treatment." (PMID 41544165, 2026). "Paclitaxel also increase EZH2 levels in the primay breast cancer and lung metastasis in vivo." (PMID 40708008, 2025). "Mechanistically, this effect in spheroids derived from MS-186 cells was accompanied by a significant reduction in the expression of EZH2, a histone methyltransferase of the polycomb repressive complex 2 (PRC2) that has been implicated in breast cancer aggressiveness and poor prognosis in TNBC." (PMID 41516003, 2025). "In breast cancer, EZH2 may induce focal adhesion kinase/TGF-β signal activation and then promote cell invasion and migration." (PMID 40028035, 2025). "In breast cancer patients, progression to advanced and metastatic disease is accompanied by decreased miR-101 and reciprocal EZH2 upregulation, and functional studies show that restoring miR-101 restrains invasion by lowering EZH2 and its repressive mark." (PMID 41301491, 2025). "Additionally, EZH2 regulates tamoxifen resistance in breast cancer through the EZH2–ERα–GREB1 transcriptional axis." (PMID 40761481, 2025). "Studies have reported that inhibitors for epigenetic modifications, such as DNA methyltransferase inhibitors, histone deacetylase inhibitors (HDACi) and EZH2 inhibitors (EZH2i), could reactivate ERα expression in basal-like breast cancer." (PMID 41318657, 2025). "Additionally, EZH2 has been shown to regulate the Hippo signaling pathway in esophageal squamous cell carcinoma and breast cancer." (PMID 40478495, 2025). "Furthermore, our research group has previously discovered that PRMT1 mediates asymmetric methylation modification on the R342 site of EZH2, leading to enhanced stability of the EZH2 protein and promotion of breast cancer metastasis." (PMID 39890802, 2025). "Besides, EZH2 phosphorylation at T367 mediated by p38 potentiates EZH2 cytoplasmic localization and its role as a mediator of metastatic progression of breast cancer." (PMID 40164592, 2025).